NRAS (NRAS proto-oncogene, GTPase)
Diseases named in the same sentence as NRAS in open-access papers (continued):
Sharing a sentence is not in itself a finding about the gene and the disease.
melanoma (continued). "In an in vivo setting, NRAS ASO treatment effectively reduced tumor growth in mice harboring NRAS-mutant melanoma xenografts, all while displaying no apparent toxic side effects." (PMID 40473796, 2025). "In this case, different BRAF-mutant melanoma cell lines were again used, as opposed to our NRAS-mutant melanoma-based study." (PMID 39996721, 2025). "COX-2 inhibition was shown to prevent human melanoma cell proliferation and induce cell death, independent of BRAF or NRAS mutations." (PMID 39941844, 2025). "The only patient with a KIT mutation developed delayed-onset brain metastases, while no patients with quadruple negative melanoma (lacking mutations in BRAF, NRAS, NF1, or KIT) developed CNS involvement." (PMID 41301010, 2025). "This subtype is associated with a lower mutational burden compared to other melanoma types, which can complicate treatment strategies, as TWT melanomas often do not respond well to targeted therapies that are effective in BRAF or NRAS mutant melanomas." (PMID 40867277, 2025). "Current treatments for melanoma face significant limitations, including low response rates (RRs), a lack of effective therapies for triple-wild-type and NRAS-mutant melanoma, and drug resistance." (PMID 41301529, 2025). "Acral melanomas, having no direct association with sun exposure, although having mutations in BRAF, NRAS, NF1, and KIT, show a lighter and different mutational burden in comparison to low-CSD or high-CSD melanomas." (PMID 38927967, 2024). "Mechanistically, we identified negative feedback on RAF dimers in NRAS mutant melanoma as the likely culprit behind their lower sensitivity to single-agent MEK inhibition and synergistic response to panRAF co-inhibition." (PMID 39199684, 2024). "However, despite the lower frequencies, BRAF, NRAS, KRAS, and KIT are somatic SNVs identified in canine melanomas, accounting for 1.8% (5/272), 8.0% (25/311), 13.1% (27/206), and 22.9% (16/70), respectively." (PMID 38397192, 2024). "Since most melanomas are BRAF mutations, NRAS mutations are rare, and not all cases have been analyzed for genetic testing; the information available is limited." (PMID 39650061, 2024). "In a multi-institutional retrospective analysis of 229 melanoma patients, 60 patients (26%) had NRAS G12/G13/Q61 mutations, 53 patients (23%) had BRAFV600 mutations, and 116 (51%) had neither NRAS/BRAF mutations." (PMID 39195270, 2024). "In agreement with the effects on Mb24 on ERK-MAPK activation, DOX-induced Mb24 expression inhibited anchorage-independent growth of NRAS-mutant cell lines but did not impact the growth of wild-type NRAS melanoma cells." (PMID 39379700, 2024). "Eight of them had not been detected by routine testing (FANCA p.W911Dfs*31 in GE02 pancreatic cfDNA, 3 NRAS p.Q61K in GE17 and GE15 melanoma and in GE11 cholangiocarcinoma, a NRAS p.G13D in GE22 pancreatic cancer, an IDH2 p.R172S in GE11 cholangiocarcinoma, and an IDH2 p.R140Q in GE14 melanoma)." (PMID 38750555, 2024). "Common mutations in BRAF and neuroblastoma RAS viral oncogene homolog (NRAS), typically present in other melanomas, are absent in this context." (PMID 39202970, 2024). "Personalized therapy in melanoma encounters a significant challenge due to the lack of precise diagnostic markers, especially in the context of BRAF/NRAS-driven melanomagenesis." (PMID 39582535, 2024). "Overall, our findings highlight the crucial role of eIF4F in regulating ERK signaling flux and suggest that pharmacological eIF4F inhibitors can disrupt the negative feedback control of MAPK activity in melanomas with BRAF and NRAS activating mutations." (PMID 39436655, 2024). "The oncogene HRAS, rather than NRAS and KRAS, is mutated in cSCCs, particularly in cSCCs occurring in melanoma patients treated with BRAF inhibitors (3–20%), and it promotes the upregulation of downstream MAPK and PI3K/AKT/mTOR signaling." (PMID 39201498, 2024).
melanoma (continued). "With regard to anatomic location, NF1 mutant tumors (n = 22/47, 46.8%), TWT melanomas (n = 14/33, 42.4%) and co-mutant tumors (n = 7/20, 35%) occurred more frequently on the head/neck compared with BRAF or NRAS mutant tumors (n = 24/154, 15.6%; p < 0.001, chi-squared test)." (PMID 38611025, 2024). "This suggests that the synergistic rather than additive response to panRAF and MEK inhibition observed in NRAS mutant vs. BRAF mutant melanoma is driven by the sensitivity to negative feedback of the former compared to the latter." (PMID 39199684, 2024). "In melanoma tumor cell lines, we did not detect any other mutation apart from the expected BRAF V600E, MAP2K1 P124S (_f1), and NRAS Q61K mutations (Dataset EV 3)." (PMID 38898234, 2024). "Here, we report on the discovery of a melanoma-associated lncRNA that we named ‘T-RECS’, and that is significantly upregulated in NRAS-/BRAF-mutated cell lines and patient tumors compared to normal/non-malignant cells or tissues." (PMID 38383439, 2024). "Driver mutations of a conventional melanoma, such as BRAF, NRAS, or NF1, should not be seen in the Spitz family." (PMID 38247727, 2024). "Moreover, it was shown that NRAS suppression resulted in increased sensitivity to vemurafenib and reduced activation of the p38 and JNK pathways in vemurafenib-resistant melanoma cell lines." (PMID 39175042, 2024). "The most common mutations in CSD and non-CSD melanomas affect BRAF, NRAS, and NF1 genes governing proliferation through action on the MAPK pathway, with BRAF and NRAS defined as oncogenes and NF1 as tumor suppressor gene." (PMID 38927967, 2024). "Previous studies identified extrachromosomal DNA (ecDNA) events in melanoma that affect the BRAF and NRAS locus, and therefore we determined whether any intrachromosomal chromothripsis events spanning these loci were actually ecDNA amplifications." (PMID 38758740, 2024). "Next, we applied the optimized pSILAC workflow to study how the immunopeptidomes of two melanoma cell lines with overactive MAPK pathway, Ma-Mel-63a (BRAF V600E) and UKE-Mel-105b (homozygous NRAS Q61R), are modulated by pharmacological inhibition of the MAPK pathway." (PMID 39835134, 2024). "Additionally, 2, 4, and 1 NF1-mutant melanomas harbored chromothripsis events spanning BRAF, NRAS, and NF1, respectively." (PMID 38758740, 2024). "We examined patients with melanoma who underwent next-generation sequencing (NGS) at a single tertiary center in South Korea, focusing on patients harboring NRAS or RAF alterations who received belvarafenib, a pan-RAF dimer inhibitor, through the Expanded Access Program (EAP)." (PMID 38470950, 2024). "ERK signaling in melanoma becomes independent of upstream feedback mechanisms because of mutations in BRAF and NRAS." (PMID 37370834, 2023). "Mutations resulting in constitutively active B-Raf proto-oncogene, serine/threonine kinase (BRAF) or NRAS proto-oncogene, GTPase (NRAS) proteins, which result in increased ERK kinase activity and, ultimately, CCND1 production, comprise 50% and 20% of all melanoma cases, respectively." (PMID 36696495, 2023). "To confirm the effectiveness of the MALAT1-targeting ASO in MALAT1-inhibition, we exposed NRAS-mutant D04 melanoma cells to non-targeting Control-ASO or MALAT1-ASO at a concentration of 50 nM for one day." (PMID 37235843, 2023). "In the context of melanoma, evidence from studies on metastatic disease demonstrates that resistance mechanisms may manifest within the PI3K or NRAS signaling pathways." (PMID 37888038, 2023).
melanoma (continued). "The non-overlapping mutations in BRAF, NRAS, and NF1 are sometimes referred to as “driver” mutations, due to their ability to independently promote growth, proliferation, and survival of melanoma cells." (PMID 37444637, 2023). "On the hand in conventional melanomas, resembling Spitz tumors or not, the initiating event is the involvement of BRAF, NRAS, KIT or NF1 mutations." (PMID 38031947, 2023). "For instance, genomic analyses have established the molecular classification of melanoma based on the most frequent driver oncogenes (BRAF, NRAS, KIT) and have also revealed a long list of rare events, whose contribution to melanoma progression toward metastasis remain mostly unclear." (PMID 37047539, 2023). "Of particular interest was the concomitant upregulation of the dual specificity phosphatases 4 and 6 (DUSP4 and 6), whose inactivation has recently emerged as digenic synthetic lethal targets in NRAS and BRAF mutant melanoma cell lines acting through ERK hyperactivation." (PMID 37946160, 2023). "MALAT1-ASO treatment significantly inhibited colony formation in vitro and reduced tumor growth in an NRAS-mutant melanoma xenograft mouse model in vivo, while showing no aberrant toxic side effects." (PMID 37235843, 2023). "One study comparing NAM (n = 54) and non-NAM acral melanoma (n = 78) revealed that, among common melanoma driver genes, mutations in KIT and KRAS were predominantly found in NAM, whereas those in BRAF and NRAS occurred almost exclusively in acral melanoma." (PMID 36983205, 2023). "Most melanoma patients have non-overlapping “driver” mutations in either BRAF, NRAS, or NF1 genes based on Next-Gen sequencing." (PMID 37444637, 2023). "Another sample showed coexisting NRAS and NF1 mutations, supporting the three-group melanoma classification (BRAF-mutant, RAS-mutant, non-BRAF-mutant/non-NRAS-mutant)." (PMID 36901733, 2023). "The large-scale analysis presented here indicates that the correlation of MALAT1 and MAPK kinase gene expression increases in melanoma and the relative expression of MALAT1 to the MAPK-pathway genes NRAS, BRAF, MEK1, MEK2, ERK1 and ERK2 is strongly reduced in melanoma, when compared to healthy skin." (PMID 37235843, 2023). "HLA-DR was detected at low, medium, and high levels in melanocytes, primary melanoma, and metastatic melanoma cells, respectively, although these biopsies contained BRAF and not the NRAS mutation, which is associated with higher HLA-DR expression." (PMID 37563418, 2023). "To accomplish this, we tested, at early and late passages, the most common genes, including HRAS, NRAS, and BRA, known to induce early-stage melanoma transformation and which are not mutated in mel-CSP." (PMID 37047372, 2023). "To determine if stable MALAT1 RNA levels are a common requirement in melanoma, we applied MALAT1-ASO treatment to a group of NRAS- and BRAF-mutant melanoma cell lines in vitro, including primary derived cell lines and cell lines with acquired resistance to the MEKi trametinib." (PMID 37235843, 2023). "From the collagen invasion assay of the spheroids, we concluded that p38 does not increase invasion, but rather decreases invasion in NRAS-mutant melanoma cells." (PMID 36765834, 2023). "In accordance with the published data, the three ALM melanomas in our cohort were not BRAF mutated; rather, they carried NRAS, KIT and NF1 mutations." (PMID 36765773, 2023). "Our results echo those of previous studies in which NRAS knockdown moderately suppressed the invasion of melanoma cells, while migration was not affected." (PMID 37083947, 2023). "In melanoma, preclinical evidence revealed that niclosamide inhibited melanoma cell proliferation in vitro, independent of BRAF or NRAS mutation status, inhibiting tumour growth in xenograft models by uncoupling mitochondria and increasing metabolic stress." (PMID 37181747, 2023).
melanoma (continued). "To further investigate the negative role of p38 in NRAS-mutant melanoma invasion, we performed two assays: immunofluorescence staining of beta-catenin and a motility assay." (PMID 36765834, 2023). "Using a large panel of patient-derived tissue samples, we further show that MALAT1 expression correlates significantly with RNA expression of genes coding for the MAPK-pathway key kinases NRAS, BRAF, MEK1/2 and ERK1/2 in healthy skin, and notably to a greater extent in melanoma." (PMID 37235843, 2023). "In this study, we have collectively demonstrated four lines of evidence to show the non-involvement of p38 in the invasion of NRAS-mutant melanoma cells." (PMID 36765834, 2023). "To gain further insight into the potential interactions between MALAT1 and MAPK pathway signaling regulators, we analyzed the expression patterns of MALAT1 with NRAS, BRAF, MEK1, MEK2, ERK1 and ERK2 in a large dataset of healthy skin and melanoma patient samples." (PMID 37235843, 2023). "Specifically, the known key oncogenic mutations in melanoma including, BRAF V600E and NRAS Q61L/R, do not have the UV-signature." (PMID 37697436, 2023). "We devised a strategy based on CRISPR-Cas9 knockout of endogenous MC1R in a human melanoma cell line wildtype for BRAF, NRAS and NF1, followed by reconstitution with epitope-labeled MC1R constructs, and functional analysis of clones expressing comparable levels of wildtype, R151C or D294H MC1R." (PMID 37762683, 2023). "GT-7 and its original compound ACA-28 were shown to induce ERK-dependent apoptosis in melanoma cell lines, harboring oncogenic BRAF or NRAS mutation, but not in the normal melanocyte (NHEM)." (PMID 35203351, 2022). "We did not identify BRAF or NRAS alterations, which are typical for the most common melanoma pathway–MAPK cascade." (PMID 35621644, 2022). "Low-CSD melanoma is likely to arise as a result of aberrations of BRAF mutation (45%) rather than RAS and NRAS mutations, which are identified in high-CSD exposure, in 15–30% and 15% of cases, respectively." (PMID 35334544, 2022). "Specifically, we could resolve the coordinated and synchronized assembly (and disassembly) of NRas and BRAF in co-clusters at the PM of live, EGF-activated 108T melanoma cells." (PMID 36304112, 2022). "Resistance to BRAF inhibitors is related to reduced cAMP levels in BRAF wild-type and NRAS wild-type melanoma cells and restoring cAMP levels using forskolin (FSK), a cAMP activator, while IBMX, a universal inhibitor of PDEs, sensitizes melanoma cells to BRAF inhibitors." (PMID 35805104, 2022). "Previously, ‘driver-negative’ (i.e. the absence of BRAF, NRAS, KIT, GNAQ or GNA11 mutations) melanoma cell-lines that were less sensitive to trametinib and which displayed paradoxical activation of MEK1/2, were found to show basal EGFR activation due to AREG." (PMID 35993275, 2022). "These subtypes are represented by BRAF mutant melanomas, which account for approximately 50% of melanomas; NRAS-, KRAS-, and HRAS-mutant melanomas, which are about 25%; NF1-mutant melanomas (15% of melanomas); and triple-wild-type melanomas, which account for the remaining 10% of cases." (PMID 35563772, 2022). "It has been reported, that NTRK fusions and typical oncogenic drivers, such as BRAF, NRAS, GNAQ and GNA11 are mutually exclusive and NTRK fusions might be more common in BRAF or NRAS wild-type melanomas." (PMID 35993275, 2022). "It has been observed that NF1 inactivating mutations occur in melanomas without BRAF and NRAS mutations and cause the activation of the MAPK pathway." (PMID 36614156, 2022).
melanoma (continued). "Typically, these panels only cover driver mutations in genes known to be involved in melanoma, such as BRAF, NRAS, KRAS, KIT, GNAQ, and GNA11, and do not include genes that have been recently found by WES/WGS studies." (PMID 36431075, 2022). "Melanomas with NF1 mutation typically occur on chronically sun-exposed skin or in older individuals, show a high mutation burden, and do not express BRAF or NRAS mutations." (PMID 36232957, 2022). "Additionally, RAS mutations have been described in two canine cutaneous melanomas (one KRAS and one NRAS) and in three melanomas of the digits (two KRAS and one NRAS)." (PMID 35202309, 2022). "Moreover, we further highlighted the role of targeting BRAF, NRAS and MC1R in melanoma prevention and treatment." (PMID 36551302, 2022). "Approximately half of all melanomas are BRAF mutants, and 20% are NRAS mutant." (PMID 34837846, 2022). "Promising preclinical data suggest that strategies combining MAPK and PI3K inhibitors may similarly prove beneficial in NRAS- and NF1-driven melanoma." (PMID 35234863, 2022). "The majority of non-CSD types, including trunk melanoma, exhibit BRAF gene V600E mutations (60%) or NRAS mutations (20%)." (PMID 35356202, 2022). "At the moment, there is no approved drug for NRAS-mutant melanoma, although MEK inhibitors are under clinical testing with some encouraging results." (PMID 35628196, 2022). "RAS-GTP levels increased in NRAS- or BRAF-mutant melanoma cells without a change in total RAS protein." (PMID 35197475, 2022). "However, the second-generation MEK inhibitor binimetinib elicited similar rates of partial response, i.e. ∼20% in patients with NRAS- and BRAF-driven melanoma in a phase II clinical trial." (PMID 35234863, 2022). "Binimetinib was the first MEK inhibitor to show activity in the treatment of NRAS-mutant melanomas, but the effects were not ideal." (PMID 36125617, 2022). "Clinical guidelines strongly recommend testing BRAF, NRAS and KIT in all melanomas." (PMID 35159047, 2022). "Subsequently, ddPCR analysis of a patient derived melanoma cell line (corresponding to a timepoint 12 months after liquid biopsy samples 4 and 9) confirmed the BRAF V600E mutation but not the NRAS Q61R mutation (ddPCR data not shown)." (PMID 35494035, 2022). "Despite this, targeted therapies are lacking against NRAS mutant melanoma and the approximately 25% of melanomas that have no identified oncogenic driver mutations." (PMID 36139469, 2022). "SOX10 immunofluorescence analysis in A375 (BRAF V600E), MeWo (wild-type for BRAF and NRAS), and 1205Lu (BRAF V600E) melanoma cell lines showed a similar level of heterogeneity and confirmed the co-presence of SOX10-low and -high expressing cells in basal culture conditions." (PMID 35296667, 2022). "Furthermore, it has been suggested that the activation of BRAF, NRAS, and PI3K can occur in various stages of melanoma development." (PMID 36614156, 2022). "The movie was captured using two-color PALM live imaging of NRas and BRAF in 108T melanoma cell." (PMID 36304112, 2022). "The ability of ID3 to contribute to the resistance to MEKi in both NRAS-mutant (WM4265.2, M93–047) and BRAF-mutant (1205Lu, WM983B) melanomas suggested that it might be a good therapeutic target for melanoma." (PMID 35187538, 2021).